SYTL2 (synaptotagmin like 2)
Description:
Isoform 1 acts as a RAB27A effector protein and plays a role in cytotoxic granule exocytosis in lymphocytes. It is required for cytotoxic granule docking at the immunologic synapse. Isoform 4 binds phosphatidylserine (PS) and phosphatidylinositol-4,5-bisphosphate (PIP2) and promotes the recruitment of glucagon-containing granules to the cell membrane in pancreatic alpha cells. Binding to PS is inhibited by Ca(2+) while binding to PIP2 is Ca(2+) insensitive.
Synonyms: KIAA1597; SGA72M; SLP2; SLP2A; FLJ20163; FLJ21219; exophilin-4; CHR11SYT; MGC102768; PPP1R151; EXO4
Tractability: Small molecule: a structure with a bound ligand is known. Antibody: UniProt places it where antibodies can reach, with high confidence; its Gene Ontology location is reachable by antibodies, with high confidence. PROTAC: ubiquitination databases record sites on it; its protein half-life has been measured.
Gene: Protein-coding gene on chromosome 11 (85,694,224 to 85,811,182, reverse strand). Ensembl gene ENSG00000137501.
Subcellular location: Cytoplasm (Isoform 1); Cell membrane; Cell membrane (Isoform 4)
Subcellular location (Human Protein Atlas): Golgi apparatus; Nucleoplasm; Plasma membrane
Pathways (Reactome):
Developmental Biology: Regulation of MITF-M-dependent genes involved in pigmentation
Gene Ontology:
Molecular function: phosphatase binding; phosphatidylinositol-4,5-bisphosphate binding; phosphatidylserine binding; protein binding; neurexin family protein binding; small GTPase binding
Biological process: exocytosis; vesicle-mediated transport; intracellular protein transport
Cellular component: cytoplasm; exocytic vesicle; plasma membrane; cytosol; melanosome; membrane; cytoplasmic vesicle
Genetic constraint (gnomAD): Loss-of-function variants: 144 observed, 175.04 expected, observed/expected ratio (o/e) 0.82, 90% interval 0.72 to 0.94. The upper end of that interval is the gene's LOEUF score, 0.94, which puts it in group 4 of 6, group 1 being the genes least tolerant of losing a copy. Missense variants: 2,717 observed, 2,552.8 expected, observed/expected ratio (o/e) 1.06, 90% interval 1.03 to 1.1. Synonymous variants: 927 observed, 918.91 expected, observed/expected ratio (o/e) 1.01, 90% interval 0.95 to 1.07.
Homologues: Orthologues: chimpanzee SYTL2 (98% identical), dog SYTL2 (74% identical), pig SYTL2 (72% identical), rabbit SYTL2 (72% identical), mouse Sytl2 (63% identical), rat Sytl2 (62% identical), macaque SYTL2 (41% identical), tropical clawed frog sytl2 (33% identical), zebrafish sytl2a (9% identical). Paralogues in human: SYTL1 (11% identical), SYTL4 (9% identical), SYTL5 (9% identical), SYTL3 (8% identical), RPH3A (6% identical), SYT7 (5% identical), SYT6 (5% identical), SYT10 (5% identical), SYT3 (5% identical), DOC2B (4% identical), SYT9 (4% identical), DOC2A (4% identical), and 19 more.
Diseases named in the same sentence as SYTL2 in open-access papers:
SYTL2 is named in the same sentence as 21 diseases in open-access papers, as found by Europe PMC text mining. Sharing a sentence is not in itself a finding about the gene and the disease. The quoted sentences say what the papers report.
ovarian carcinoma (5 papers, 2019 to 2021). A malignant neoplasm originating from the surface ovarian epithelium. "It has been demonstrated that SYTL2 contributes in the ovarian cancer, and can also promote the metastatic potential in ovarian cancer when it is overexpressed." (PMID 34236536, 2021). "In ovarian cancer, with over-expression of SYTL2 (synaptotagmin like 2) mRNA, the methylation rate in specific CpG sites of the SYTL2 promoter decreased, which significantly promoted migration and invasion of ovarian cancer cells." (PMID 33996533, 2021). "Reportedly, miR-654-3p targets several genes associated with malignancy, such as P21 in gastric cancer, AKT3 in ovarian cancer, and SYTL2 in osteosarcoma." (PMID 33193697, 2020). "Synaptotagmin-like protein 2 (SYTL2) was previously identified to increase the metastatic potential of ovarian cancer." (PMID 32351327, 2020).
prostate carcinoma (4 papers, 2007 to 2025). A carcinoma that arises from epithelial cells of the prostate gland. "SYTL2 was among the androgen down-regulated genes, and has been previously shown to be differentially regulated by AR reduction in prostate cancer cells." (PMID 17553164, 2007). "Among the hormone and DDC down-regulated genes was the SYTL2 gene, which was previously shown to be positively regulated by AR reduction in androgen-ablated prostate cancer cells." (PMID 17553164, 2007). "By influencing the splicing of genes such as ATG13 and SYTL2, PD‐L1 may alter the functional output of these proteins, which could ultimately contribute to the development and progression of castration‐resistant prostate cancer." (PMID 40923331, 2025).
osteosarcoma (3 papers, 2020 to 2023). A usually aggressive malignant bone-forming mesenchymal neoplasm, predominantly affecting adolescents and young adults. "Upregulated RAB27A, SYTL2, and VWF expression was confirmed in two human ASPS cell lines, ASPS-KY and ASPS1, in comparison with two Ewing sarcomas, two synovial sarcomas, and one osteosarcoma cell line." (PMID 37029109, 2023).
breast carcinoma (2 papers, 2016 to 2018). "The highest inductions were for GLIPR1 (~30-fold), a gene hormonally-regulated in breast cancer cells, and SYTL2 (~12-fold), a trafficking protein also known as Breast Cancer-Associated antigen SGA-72M." (PMID 27351228, 2016).
sarcoma (2 papers, 2022 to 2023). A usually aggressive malignant neoplasm of the soft tissue or bone. "Increased RAB27A, SYTL2, and VWF expression was observed in human ASPS among the six sarcoma types." (PMID 37029109, 2023).
psoriasis (1 paper, 2019). An autoimmune condition characterized by red, well-delineated plaques with silvery scales that are usually on the extensor surfaces and scalp. "We observed significant increases in protein expression of CMKLR-1, COL8A-1, NRK, and SYTL-2 in DMSCs from patients with psoriasis compared with those from healthy donors, whereas the expression level of SFRP-2 was obviously decreased." (PMID 30760317, 2019). "In the present study, the downregulation of SFRP2 and overexpression of CMKLR, COL8A, NRK, and SYTL2 reported herein revealed enhanced migratory and invasive potential abilities from DMSCs to other cells in psoriasis, which may be beneficial to the immunomodulatory properties of MSCs." (PMID 30760317, 2019). "We observed the upregulation of CMKLR-1, COL8A-1, NETO-2, NRK, SYTL-2, and SULF-2 in dermal mesenchymal stem cells derived from patients with psoriasis at both mRNA and protein level, however, a significant downregulation of SFRP-2 between two groups." (PMID 30760317, 2019).
cancer (4 papers, 2021 to 2023). A tumor composed of atypical neoplastic, often pleomorphic cells that invade other tissues. "Among those genes, only DAPK1 and SYTL2 have been implicated in cancers." (PMID 35487942, 2022). "We determined that SYTL2 serves as a regulator of pseudopodia formation in cancer metastasis." (PMID 37147713, 2023).
tumor (4 papers, 2023 to 2024). "In the present study, we revealed that a high expression level of SYTL2 was correlated with a high rate of metastasis, an advanced clinical tumor stage and a poor prognosis in PCa samples." (PMID 37147713, 2023). "During 5 days of co-culturing, significant HUVEC sprouting toward the tumor spheroids of ASPS cells occurred; however, the sprouting effect was significantly suppressed by Rab27a or Sytl2 knockout and ASPSCR1::TFE3-expression loss." (PMID 37029109, 2023). "Despite comparable proliferation rates in vitro, significant suppression of in vivo tumor development was observed by Pdgfb, Rab27a, Sytl2, and Vwf knockout." (PMID 37029109, 2023). "Moreover, SYTL2 expression was much higher in mPCa samples than in localized and tumor-adjacent samples." (PMID 37147713, 2023). "Synaptotagmin-like 2 (SYTL2) is intertwined with high metastasis rates, advanced tumor staging, and poor prognosis in PCa." (PMID 39055653, 2024).
SYTL2 also shares sentences with these, for which no sentence is quoted: albinism (1 paper); Alzheimer disease (1); bladder cancer (1); colon carcinoma (1); Ewing sarcoma (1); gastric cancer (1); gastrointestinal carcinoma (1); Griscelli syndrome (1); hemophagocytic lymphohistiocytosis (1); Immunodeficiency (1); renal carcinoma (1); synovial sarcoma (1); T-cell leukemia (1).